S100B (S100 calcium binding protein B)
Diseases named in the same sentence as S100B in open-access papers (continued):
Sharing a sentence is not in itself a finding about the gene and the disease.
hypoxic-ischemic encephalopathy (8 papers, 2012 to 2025). "Higher S100B concentrations in calves with perinatal asphyxia compared to healthy calves have been associated with the development of hypoxic-ischemic encephalopathy." (PMID 36428450, 2022). "In term and preterm infants with hypoxic-ischemic encephalopathy, S100B concentration was found to be elevated within the first 72 h." (PMID 36428450, 2022). "UCHL1 and S100B were found to be useful markers of hypoxic-ischemic encephalopathy in calves with perinatal asphyxia." (PMID 36428450, 2022). "UCHL1 and S100B concentrations were found to be useful markers for the determination of hypoxic-ischemic encephalopathy in calves with perinatal asphyxia." (PMID 36428450, 2022). "Most important, UCHL1 and S100B concentrations were found to be useful markers for the determination of hypoxic-ischemic encephalopathy in calves with perinatal asphyxia." (PMID 36428450, 2022). "In another study of 132 term infants, urinary S100B concentrations were higher in infants who suffered perinatal asphyxia or died and urine S100B above 1 mcg/L predicted neonatal death with a sensitivity and specificity of 100%." (PMID 23130015, 2012). "Cord S100B concentrations were higher in case of perinatal asphyxia and HIE." (PMID 25685774, 2015). "S100B concentrations in the cerebrospinal fluid (CSF) were a reliable biomarker among neonates with perinatal asphyxia in the evaluation of brain lesion extent and correlated with the neurologic impairment at one year of age as well as with death before one year." (PMID 25685774, 2015). "Previous studies showed that in the umbilical cord blood of infants born with neonatal asphyxia S100B and lactate concentrations were increased, and these markers could be helpful as an early predictive marker for diagnosis of neonatal hypoxic-ischemic encephalopathy." (PMID 36428450, 2022). "In our study, the concomitant elevation of S100B, lactate, and UCHL1 concentrations in calves with perinatal asphyxia supports the development of hypoxic-ischemic encephalopathy." (PMID 36428450, 2022). "However, no studies examining S100B in relation to treatment response in perinatal depression were found, representing an opportunity for investigation." (PMID 41440970, 2025).
neurofibroma (8 papers, 2012 to 2025). An intraneural or extraneural neoplasm arising from nerve tissues and neural sheaths. "In the GeneCards database, two diseases are associated with S100B gene, syringoma, and neurofibroma." (PMID 37817005, 2024). "Immunohistochemistry for H3K27 trimethylation, an epigenetic marker of PRC2 activity, and immunohistochemistry for the Schwann cell differentiation marker S100B demonstrated loss of each in Group 1 tumors compared to Group 2/3 histological neurofibromas and MPNSTs." (PMID 38216572, 2024). "Neurofibroma tumor nuclei remain most similar to Schwann cells, with expression of markers such as S100B, PMP2, MPZ and ERBB3." (PMID 37164978, 2023). "H&E staining of tissue sections showed features of neurofibroma-like lesion with spindle shape cells, anti-S100β+ SCs, and toluidine blue–positive mast cells." (PMID 31032403, 2019). "In accordance with this hypothesis, S100β−/NF1− cells are detected in high proportion (16–31%) in neurofibromas." (PMID 22550514, 2012). "Similarly, characterization of cells present in neurofibromas by S100β, a marker for the Schwann lineage, has demonstrated that a nullizygous population (NF1−/−) that is negative for S100β expression is present in neurofibromas." (PMID 22550514, 2012). "Moreover, a nullizygous population of cells that is S100β negative is present in human neurofibromas, and NF1+/− multipotent progenitor cells are seemingly recruited to the tumor." (PMID 22550514, 2012).
preeclampsia (8 papers, 2017 to 2026). Preeclampsia is a hypertensive disorder of pregnancy that is characterized by new-onset hypertension with proteinuria presenting after 20 weeks of gestation, and depending on mild or severe forms may initially present with severe headache, visual disturbances, and hyperreflexia. "In this systematic review, we aimed to investigate the association between maternal blood (serum or plasma) S100B levels and preeclampsia, focusing on its predictive value and correlation with the severity of the disease, with a particular focus on neurological symptoms." (PMID 40563479, 2025). "One reason could be that the signal from S100B produced in other extracerebral tissues such as muscle cells and fat cells are dominating causes to increased serum concentrations in preeclampsia." (PMID 33556141, 2021). "All of the studies revealed that S100B blood levels were higher in preeclampsia compared to uncomplicated pregnancies before onset, after its diagnosis, and one year postpartum." (PMID 40563479, 2025). "CSF and blood at delivery from 15 women with preeclampsia and 15 women with normal pregnancies were analysed for the cerebral biomarkers S100B, NSE, tau protein and NfL by Simoa and ELISA based methods." (PMID 33556141, 2021). "Women with preeclampsia demonstrated increased serum concentrations of S100B (0.08 vs 0.05 ug/L, p<0.01) and plasma concentrations of NfL (9.29 vs 5.44 pg/ml, p<0.001) compared to women with normal pregnancies." (PMID 33556141, 2021). "S100B was the first cerebral biomarker that was reported to be increased in plasma in preeclampsia with severe features by our group and others and in addition, women with visual disturbances demonstrated an increased plasma concentration of S100B." (PMID 33556141, 2021). "A combined model for preeclampsia with tau, neurofilament light chain, S100B and neuron specific enolase in gestational week 25 displayed an area under the curve of 0.77, in week 28 it was 0.75, in week 33 it was 0.89 and in week 37 it was 0.83." (PMID 29719006, 2018). "The secondary aim was to evaluate the potential cerebral involvement in women with preeclampsia before onset of disease in a combination model with peripheral concentrations of NfL, tau, S100B and NSE." (PMID 29719006, 2018). "However, S100B remains the most extensively studied biomarker of brain injury, not only in the context of preeclampsia but also across a broad range of neurological pathologies." (PMID 40563479, 2025). "Plasma concentrations of NfL, tau, NSE and S100B were all higher in women with preeclampsia compared with women with normal pregnancies (8.85 vs. 5.25 ng/L, p < 0.001; 2.90 vs. 2.40 ng/L, p < 0.05; 3.50 vs. 2.37 μg/L, p < 0.001 and 0.08 vs. 0.05 μg/L, p < 0.01, respectively)." (PMID 35269411, 2022). "In addition, we corroborated previous findings of higher plasma concentrations of the cerebral biomarkers NfL, tau, NSE and S100B in women with preeclampsia compared with women with normal pregnancies." (PMID 35269411, 2022). "However, several studies have established a correlation between serum or plasma concentrations of S100B, which as of now is the most explored of the cerebral biomarkers in preeclampsia, and severity of disease and/or neurological symptoms." (PMID 35269411, 2022). "Thus, alternative extracerebral sources of tau, NSE and S100B in preeclampsia have to be considered." (PMID 33556141, 2021). "Our group and others have showed that peripheral concentrations of the cerebral biomarkers S100B, neuron specific enolase (NSE), tau protein and neurofilament light chain (NfL) are increased in preeclampsia both before onset, during disease and postpartum." (PMID 33556141, 2021). "Studies have also reported higher S100B plasma concentrations in women with severe preeclampsia and eclampsia compared with women with preeclampsia without severe features." (PMID 35269411, 2022). "Our results showed that S100B was increased in serum but not in CSF in preeclampsia." (PMID 33556141, 2021).
preeclampsia (continued). "The results of this study support these findings regarding S100B and NfL but we could not reproduce earlier findings of increased NSE and tau plasma concentrations in preeclampsia." (PMID 33556141, 2021). "In this study, plasma from women with preeclampsia (n = 28), women with normal pregnancies (n = 28) and non-pregnant women (n = 16) was analyzed for concentrations of the cerebral biomarkers neurofilament light (NfL), tau, neuron-specific enolase (NSE) and S100B." (PMID 35269411, 2022).
autism (7 papers, 2012 to 2023). Persistent deficits in social interaction and communication and interaction as well as a markedly restricted repertoire of activity and interest as well as repetitive patterns of behavior. "Here, we hypothesize that hypozincemia induced by increased levels of S100B during brain development will affect synapse function and maturation, possibly via the autism-associated SHANK protein complex at the PSD." (PMID 34741005, 2021). "This may indicate that the extent of the elevation of serum S100B protein levels was closely linked to the degree of the severity of autism." (PMID 22420334, 2012). "Autistic children also showed significantly higher serum S100B levels than healthy controls, and S100B protein levels were significantly correlated to the severity of autism." (PMID 34741005, 2021). "S100B protein levels were elevated in autistic children, and they were significantly correlated with the degree of the severity of autism." (PMID 22420334, 2012). "Researchers in a previous study reported that risperidone, a drug used to improve autism symptoms, induced a statistically significant increment of about 80% of S100B protein secretion." (PMID 22420334, 2012). "Children with severe autism had significantly higher serum S100B protein than patients with mild to moderate autism (P = 0.01)." (PMID 22420334, 2012). "Patients with severe autism had significantly higher serum S100B protein levels (222.47 ± 52.95 pg/ml) than children with mild to moderate autism did (191.53 ± 47.89 pg/ml) (P = 0.01)." (PMID 22420334, 2012). "In the present work, patients with severe autism had significantly higher serum S100B protein levels than children with mild to moderate autism (P = 0.01)." (PMID 22420334, 2012). "Higher S100B levels in children with severe ASD than in mild-to-moderate autism were detected." (PMID 37759935, 2023). "However, further research is warranted to investigate the possible link between serum S100B protein levels and other autoantibodies, which are possible indicators of autoimmunity to central nervous system in autism." (PMID 22420334, 2012). "However, further research is warranted to investigate the possible link between serum S100B protein levels and other autoantibodies, which are possible indicators of autoimmunity to CNS, in autism." (PMID 22420334, 2012). "The increased serum levels of S100B protein may be attributable to other factors that may participate in neurological damage in autism." (PMID 22420334, 2012). "Because autoantibodies can cross the BBB and combine with brain tissue antigens to form immune complexes that result in neurological damage, we have tried to find a possible link between the elevated serum levels of S100B protein and antiribosomal P protein antibodies in autism." (PMID 22420334, 2012). "Astrocytes are the most abundant source of S100B in human brain; given the importance of these cells in the neurodevelopment and in the neuroarchitecturing, further studies could confirm their role in autism pathogenesis." (PMID 30577568, 2018). "However, it is not easy to determine whether the increase in serum S100B protein levels is a mere consequence of autism or has a pathogenic role in the disease." (PMID 22420334, 2012). "The higher levels of MAP-2, NFP, MBP, MAG, α-synuclein S100B and GFAP (3.2 to 4.8-fold) autoantibodies reported in ASD children warrant further research for developing autoantibodies screening as a biomarker for detection of early autism." (PMID 31035713, 2019).
bacterial meningitis (7 papers, 2009 to 2025). Inflammation of the membranes surrounding the brain and spinal cord due to a bacterial infection. "S100B also plays a role in the pathogenesis of sepsis-associated encephalopathy and bacterial meningitis (BM) in children." (PMID 38115295, 2023). "The correlations between S-100B and oxidative stress/antioxidant markers for causal relationship for the severity and neurological complications of bacterial meningitis were discussed." (PMID 19814795, 2009). "CSF levels of HBP and NGAL and the blood level of S100B in the bacterial meningitis group were significantly higher (p < 0.05)." (PMID 35740230, 2022). "Elevated S100B levels are observed in encephalitis and bacterial meningitis, but remain unaltered in viral meningitis." (PMID 31093802, 2019). "Further investigations, however, revealed that S100B in serum or CSF exhibited suboptimal sensitivity and specificity for bacterial meningitis." (PMID 28670576, 2017). "The highest, but still inconsistent, levels of S100B in CSF and serum were seen in viral encephalitis or in bacterial meningitis complicated by ventriculitis or obvious parenchymal abnormalities on brain imaging." (PMID 28670576, 2017). "The relationship between S-100B and oxidative stress/antioxidant mechanisms in patients with bacterial meningitis is barely determined." (PMID 19814795, 2009). "Further experimental studies are needed to confirm the direct or indirect causal relationship between bacteria, inflammation, oxidative stress and S-100B, markers in the pathogenesis of bacterial meningitis." (PMID 19814795, 2009). "In addition, the blood levels of S100B were significantly higher in the group with bacterial meningitis (166.30 vs. 92.04 ng/mL, p < 0.05)." (PMID 35740230, 2022). "The exact mechanisms that regulate the increased intrathecal levels of S-100B protein in bacterial meningitis are unknown." (PMID 19814795, 2009). "This study suggests that loss of integrity of brain-CSF barriers, oxidative stress and S-100B may contribute to the severity and neurological complications of bacterial meningitis." (PMID 19814795, 2009). "Both levels of S100B and of NSE were studied as potentially useful biomarkers in patients with bacterial meningitis, with promising results." (PMID 35740230, 2022). "After eliminating data sets without HBP, NGAL, S100B, and NSE values, the study groups comprised 72 cases, of which 41 patients had bacterial meningitis and 31 had viral meningitis." (PMID 35740230, 2022).
Gliosis (7 papers, 2017 to 2023). Gliosis is the focal proliferation of glial cells in the central nervous system. "Considering the existence of this unique cell population that lacks the common glial marker, as well as evidence that S100β plays critical roles in astrocyte activation and migration, our data demonstrates the presence of gliosis in our canine model." (PMID 37304080, 2023). "Markers indicative of gliosis were further investigated by examining patterns of immunoreactivity for GFAP, S100-β, and neurocan (NCAN)." (PMID 28381236, 2017).
head injury (7 papers, 2018 to 2025). Injury to the head. "In patients with mild head injuries, S100B levels peak immediately after the trauma but decline sharply, reaching below detection limits (0.0002 μg/L) within six hours due to its short half-life of approximately 30 minutes." (PMID 40599519, 2025). "In these conditions, we have recently demonstrated the interest of incorporating S100B measurement to the Head Injury Assessment (HIA) protocol in the management of concussed professional rugby players." (PMID 37047574, 2023). "The most recent validation of the Scandinavian Head Injury Guideline with a cutoff of 100 pg/ml of S100B within 6 hrs of mild head injury showed a sensitivity of 0.94 and a specificity of 0.19 in predicting abnormalities on CT scan." (PMID 34530937, 2021). "SNC – Scandinavian Neurotrauma Committee, CHIPPR – CT in Head Injury Patients Prediction Rule, NOHCTR – New Orleans Head CT Rule, CCTHR – Canadian CT Head Rule, NICE – the National Institute for Health and Care Excellence, GCS – Glasgow Coma Scale, S100B – calcium binding protein B." (PMID 40165992, 2025). "Especially, while S100B has been suggested to be one of the strongest biomarkers to detect head injuries, previous studies on athletes competing in non-contract sports such as swimming, running and basketball showed increased level of S100B independently of head impact history." (PMID 38182718, 2024).
meningioma (7 papers, 2006 to 2023). A generally slow growing tumor attached to the dura mater. "Recently, the immunohistochemistry (IHC) markers S100B, SCGN, ACADL and MCM2 have been shown to be associated with underlying biological subtypes of meningioma (MG1-MG4)." (PMID 36685704, 2023). "Among four prognostically distinct molecular subgroups, meningiomas with the most favorable outcome showed exceptionally high levels of S100B levels in the proteome-analysis." (PMID 35838837, 2023). "In total, 244 patients with meningiomas with tissue in TMAs were included and the IHC markers S100B, SCGN, ACADL and MCM2 were analyzed." (PMID 36685704, 2023). "Included were fifty two consecutive adult patients undergoing surgery for meningioma that provided blood samples for determination of S100B concentrations." (PMID 18803814, 2008). "A recent study of patients who underwent meningioma resection demonstrated that pathologically increased serum S100β concentrations in the early postcraniotomy period correlated with neurological deterioration." (PMID 17020600, 2006). "• Serum S100β levels perform poorly as an indicator of tumour characteristics for patients with meningiomas." (PMID 17020600, 2006). "The current study was therefore conducted to examine the correlation between serial serum S100β protein levels and pre- and postcraniotomy MRI/computed tomography (CT) findings and neurological deterioration in patients undergoing meningioma resection." (PMID 17020600, 2006). "In 52 consecutive patients admitted for meningioma surgery, serum S100β levels were determined upon admission and immediately, 24 hours, and 48 hours after surgery." (PMID 17020600, 2006). "In this regard, there is evidence that increased levels of the calcium-binding protein S100B may be of use to identify meningiomas with a better progression-free survival." (PMID 35838837, 2023). "Serum S100β levels may serve as a potentially useful early marker of postcraniotomy brain damage in patients undergoing elective meningioma resection." (PMID 17020600, 2006). "In patients with meningioma, serum S100β levels perform poorly as an indicator of tumour characteristics but may suggest ongoing postcraniotomy injury." (PMID 17020600, 2006). "This study evaluated whether pre-/postoperative serum S100β levels correlate with unfavourable clinical and radiological findings in patients undergoing elective meningioma resection." (PMID 17020600, 2006). "In patients with meningioma, serum S100β levels perform poorly as an indicator of tumour characteristics but may provide an early sign of postcraniotomy injury." (PMID 17020600, 2006). "Moreover, the hypothesis that S100B levels can be used as an early biomarker in post-craniotomy brain damage in meningioma patients was verified." (PMID 28761630, 2017). "ANOVA did not demonstrate a difference in S100β levels at any of the examined times between meningiomas with different degrees of vascularity (high, medium, and low)." (PMID 17020600, 2006). "For this study, we established primary meningioma cultures comprised of epithelial-like cells expressing vimentin, epithelial membrane antigen (EMA), and S100β, but not glial fibrillary astrocytic protein (GFAP)." (PMID 25247996, 2014).